EIF6 (eukaryotic translation initiation factor 6)
Description:
Binds to the 60S ribosomal subunit and prevents its association with the 40S ribosomal subunit to form the 80S initiation complex in the cytoplasm. Behaves as a stimulatory translation initiation factor downstream insulin/growth factors. Is also involved in ribosome biogenesis. Associates with pre-60S subunits in the nucleus and is involved in its nuclear export. Cytoplasmic release of TIF6 from 60S subunits and nuclear relocalization is promoted by a RACK1 (RACK1)- dependent protein kinase C activity. In tissues responsive to insulin, controls fatty acid synthesis and glycolysis by exerting translational control of adipogenic transcription factors such as CEBPB, CEBPD and ATF4 that have G/C rich or uORF in their 5'UTR. Required for ROS-dependent megakaryocyte maturation and platelets formation, controls the expression of mitochondrial respiratory chain genes involved in reactive oxygen species (ROS) synthesis (By similarity). Involved in miRNA-mediated gene silencing by the RNA-induced silencing complex (RISC). Required for both miRNA-mediated translational repression and miRNA-mediated cleavage of complementary mRNAs by RISC. Modulates cell cycle progression and global translation of pre-B cells, its activation seems to be rate-limiting in tumorigenesis and tumor growth (By similarity).
Synonyms: eIF-6; EIF3A; ITGB4BP; p27BBP; b(2)gcn; CAB; p27(BBP)
Tractability: Small molecule: a structure with a bound ligand is known. PROTAC: UniProt records ubiquitination sites on it; its protein half-life has been measured.
Gene: Protein-coding gene on chromosome 20 (35,278,906 to 35,284,985, reverse strand). Ensembl gene ENSG00000242372.
Subcellular location: Cytoplasm; Nucleus, nucleolus
Subcellular location (Human Protein Atlas): Nucleoplasm
Gene Ontology:
Molecular function: protein binding; ribosome binding; ribosomal large subunit binding; translation initiation factor activity
Biological process: cytosolic ribosome assembly; miRNA-mediated gene silencing by inhibition of translation; miRNA-mediated post-transcriptional gene silencing; assembly of large subunit precursor of preribosome; maturation of 5.8S rRNA; maturation of LSU-rRNA; positive regulation of translation; regulation of fatty acid biosynthetic process; regulation of glycolytic process; regulation of megakaryocyte differentiation; regulation of reactive oxygen species metabolic process; response to insulin; ribosomal subunit export from nucleus; ribosomal large subunit biogenesis; translational initiation
Cellular component: cytoplasm; extracellular exosome; nucleoplasm; nucleus; intermediate filament; lamin filament; nucleolus; synapse
Genetic constraint (gnomAD): Loss-of-function variants: 10 observed, 27.23 expected, observed/expected ratio (o/e) 0.37, 90% interval 0.23 to 0.62. The upper end of that interval is the gene's LOEUF score, 0.62, which puts it in group 2 of 6, group 1 being the genes least tolerant of losing a copy. Missense variants: 246 observed, 324.92 expected, observed/expected ratio (o/e) 0.76, 90% interval 0.68 to 0.84. Synonymous variants: 122 observed, 129.34 expected, observed/expected ratio (o/e) 0.94, 90% interval 0.81 to 1.1.
Homologues: Orthologues: chimpanzee EIF6 (100% identical), mouse Eif6 (98% identical), rabbit EIF6 (98% identical), dog EIF6 (97% identical), pig EIF6 (97% identical), guinea pig EIF6 (96% identical), tropical clawed frog eif6 (92% identical), zebrafish eif6 (91% identical), rat Eif6-ps1 (87% identical), Drosophila melanogaster eIF6 (78% identical), macaque EIF6 (78% identical), Caenorhabditis elegans eif-6 (64% identical).
Diseases named in the same sentence as EIF6 in open-access papers:
EIF6 is named in the same sentence as 79 diseases in open-access papers, as found by Europe PMC text mining. Sharing a sentence is not in itself a finding about the gene and the disease. The quoted sentences say what the papers report.
hepatocellular carcinoma (9 papers, 2021 to 2025). A malignant tumor that arises from hepatocytes. "Pharmacologic inhibition of eIF6 activity is associated with metabolic rewiring related to hepatocellular carcinoma." (PMID 39409166, 2024). "Although emerging studies indicate that eIF6 is aberrantly expressed in various types of cancers, the functions and underlying molecular mechanisms of eIF6 in the pathological progression of hepatocellular carcinoma (HCC) remain unclear." (PMID 34016142, 2021). "On the other hand, an attenuated eIF6-driven translation can contribute to lipid accumulation in the progression of nonalcoholic fatty liver disease to hepatocellular carcinoma." (PMID 39951526, 2025). "eIF6 inhibition using these novel compounds has shown promising results in hepatocellular carcinoma in vitro." (PMID 39409166, 2024). "EIF6 triggers mammalian target of rapamycin signaling in hepatocellular carcinoma, leading to enhanced proliferation and invasion." (PMID 38157850, 2024). "Recently, our group has shown that eIF6 haploinsufficiency protects from hepatic steatosis fibrosis and the progression to hepatocellular carcinoma in vivo." (PMID 36902316, 2023). "Earlier studies have suggested that eIF6 is up-regulation in hepatocellular carcinoma, lung adenocarcinoma, and colorectal cancer." (PMID 35707354, 2022). "We analyzed a total of 424 eIF6 expression profiles from the TCGA liver carcinoma dataset, including 50 normal tissues and 374 tumor tissues." (PMID 34016142, 2021). "The overexpression of EIF6 correlates with the poor prognosis of patients in many cancers, including gall bladder cancer, lung adenocarcinoma, esophagus adenocarcinoma, hepatocellular carcinoma, melanoma, and colorectal cancer." (PMID 38157850, 2024). "Additionally, this hypothesis has also been proven because eIF6 knock-down could efficiently inhibit the progression of hepatocellular carcinoma and non-small cell lung carcinoma." (PMID 35707354, 2022). "In addition, eIF6 depletion delays the progression from NAFLD to hepatocellular carcinoma, in vivo." (PMID 34385447, 2021). "Furthermore, eIF6 has been shown to play a vital role as a driver and prognostic marker in multiple cancers, including breast cancer, colorectal carcinoma, ovarian adenocarcinoma, non-small-cell lung cancer, lung adenocarcinoma, esophageal carcinoma, hepatocellular carcinoma, and glioblastoma." (PMID 39409166, 2024). "eIF6 levels increase throughout the progression from Non-Alcoholic Fatty Liver Disease (NAFLD) to hepatocellular carcinoma." (PMID 34385447, 2021). "Previous studies demonstrated that eIF6 is highly expressed in human cancers such as colorectal cancer, hepatocellular carcinoma, ovarian serous carcinoma, acute promyelocytic leukemia, non-small cell lung cancer, and affect lymphoma genesis and tumor progression." (PMID 35794622, 2022).
Shwachman-Diamond syndrome (7 papers, 2020 to 2025). "Impaired function of eIF6 contributes to the underlying pathology of certain cancers and inherited ribosomopathies: Shwachman–Diamond Syndrome (SDS) and a subset of pediatric T-cell acute lymphoblastic leukemia." (PMID 36651285, 2023). "The release factors SBDS and EFL1—both mutated in the leukemia predisposition disorder Shwachman-Diamond syndrome — license entry of nascent 60S ribosomal subunits into active translation by evicting the anti-association factor eIF6 from the 60S intersubunit face." (PMID 35322020, 2022). "Here, we establish that acquired mutations in the EIF6 gene are a frequent mechanism of SGR in Shwachman-Diamond syndrome (SDS), a leukemia predisposition disorder caused by a germline defect in ribosome assembly." (PMID 34413298, 2021). "Shwachman-Diamond syndrome (SDS) is a leukemia predisposition disorder that is caused by defective release of eIF6 during ribosome assembly." (PMID 34413298, 2021).
colorectal cancer (6 papers, 2021 to 2025). A primary or metastatic malignant neoplasm that affects the colon or rectum. "Furthermore, the increased eIF6 level has been reported to play a major role in association with poor prognostication of colorectal cancer, non-small cell lung carcinoma and malignant pleural mesothelioma." (PMID 35707354, 2022). "In colorectal cancer, EIF6 activates AKT-related cellular signaling to increase tumorigenesis by modulating cell proliferation, cell cycle, and apoptosis." (PMID 38157850, 2024). "eIF6 has been reported as an essential regulator in liver hepatocellular carcinoma, colorectal carcinoma, and non-small cell lung carcinoma, respectively." (PMID 35707354, 2022). "Dysregulation of eIF6 function and expression has been previously discovered in various types of malignancies, including breast cancer, colorectal carcinoma (CRC), malignant pleural mesothelioma (MPM) and ovarian adenocarcinoma." (PMID 36435920, 2023). "Furthermore, increasing studies confirm dysregulation of eIF6 has been shown in various cancer entities, such as colorectal carcinoma (CRC), malignant pleural mesothelioma (MPM), ovarian adenocarcinoma (OV), breast cancer (MBC) and non-small cell lung cancer (NSCLC)." (PMID 34016142, 2021). "Furthermore, recent studies approved that eIF6 was dysregulated in various cancers, such as malignant pleural mesothelioma (MPM), Gallbladder cancer (GBC), ovarian serous carcinoma (OV), colorectal cancer (CRC) and non-small cell lung cancer (NSCLC)." (PMID 34016142, 2021).
triple-negative breast carcinoma (6 papers, 2022 to 2025). An invasive breast carcinoma which is negative for expression of estrogen receptor (ER), progesterone receptor (PR), and human epidermal growth factor receptor 2 (HER2). "Circ-EIF6, encoding the novel peptide EIF6-224aa, enhances proliferation and metastasis of triple-negative breast cancer cells by activating the MYH9/Wnt/β-catenin pathway." (PMID 38383479, 2024). "Circ-EIF6 encodes EIF6-224aa which acts as a prognostic and therapeutic target in triple-negative breast cancer." (PMID 36620552, 2022). "Moreover, circRNA Circ-EIF6 encodes EIF6-224aa to promote triple-negative breast cancer progression via stabilizing MYH9 and activating Wnt/beta-catenin pathway in mammals." (PMID 38361078, 2024). "In triple-negative breast cancer, circRNA EIF6-224aa directly interacts with MYH9, inhibiting MYH9 degradation through the ubiquitin-proteasome pathway and activating the Wnt/β-catenin signaling pathway." (PMID 39988672, 2025). "CircRNA EIF6-224aa directly interacts with the MYH9 protein and impedes MYH9 degradation by suppressing the ubiquitin-proteasome pathway, subsequently activating the Wnt/beta-catenin signalling pathway in triple-negative breast cancer." (PMID 37875476, 2023).
breast carcinoma (5 papers, 2014 to 2025). "In breast cancer, a few studies have shown that circRNAs encode peptides, including circ-EIF6, which encodes EIF6-224aa; circ-HER2, which encodes HER2-103; and circSEMA4B, which encodes SEMA4B-211aa, which reportedly participate in the progression and drug resistance of tumors." (PMID 38755678, 2024). "SEMA4B‐211aa and EIF6‐224aa have been confirmed to regulate the formation and development of breast cancer." (PMID 36644969, 2023).
leukemia (5 papers, 2017 to 2025). A malignant (clonal) hematologic disorder, involving hematopoietic stem cells and characterized by the presence of primitive or atypical myeloid or lymphoid cells in the bone marrow and the blood. "In patients with SDS, somatic EIF6 mutations provide a compensatory mechanism that is protective against disease transformation to leukemia." (PMID 37816584, 2023). "Our results support EIF6 as a potential therapeutic target in SDS patients, since pharmacologic inactivation of EIF6 could mimic genetic inactivation of EIF6, thereby reducing leukemia risk and improving hematopoietic function in SDS patients." (PMID 33637765, 2021). "We cloned patient-derived mutations with different predicted functional consequences and generated K562 leukemia cell lines that expressed wild-type or mutant EIF6 cDNA with a C-terminal V5-epitope tag under the control of a doxycycline-inducible promoter." (PMID 33637765, 2021). "Previous studies have reported eIF6 overexpression in ovarian serous carcinoma, leukemia, head and neck carcinoma, as well as CRC." (PMID 29254159, 2017).
lung adenocarcinoma (5 papers, 2022 to 2026). A carcinoma that arises from the lung and is characterized by the presence of malignant glandular epithelial cells. "EIF6 expression positively correlates with stemness-associated genes in lung adenocarcinoma cells, and knocking out EIF6 improved prognosis in mice." (PMID 38157850, 2024). "However, little was known about the association between eIF6 and lung adenocarcinoma (LUAD) progression." (PMID 36435920, 2023). "In eIF6 over-expression specimens, the survival rates of brain lower-grade glioma (LGG), liver hepatocellular carcinoma (LIHC), lung adenocarcinoma (LUAD), pancreatic adenocarcinoma (PAAD), and skin cutaneous melanoma (SKCM) were all significantly reduced." (PMID 35707354, 2022).
lung carcinoma (4 papers, 2017 to 2026). "This study evaluated the biological roles of eIF6 in lung cancer and found the associations between eIF6 and malignant features of lung cancer." (PMID 36435920, 2023). "However, to the best of our knowledge, the potential association between eIF6 and lung cancer remain poorly understood." (PMID 36435920, 2023). "Apart from previous studies, this paper further indicated the functional roles of eIF6 in modulating tumor stemness and identified eIF6 as a therapeutical target in lung cancer." (PMID 36435920, 2023). "Additional tumor models would need to be applied for assessing the clinical efficacy of eIF6 inhibition in LUAD treatment, including patient-derived xenografts, patient-derived organoid and orthotopic human lung cancer models." (PMID 36435920, 2023).
malignant pleural mesothelioma (4 papers, 2015 to 2023). A malignant neoplasm that arises from mesothelial cells in the pleura and shows a diffuse growth pattern. "A reduction in eIF6 levels in malignant pleural mesotheliomas and in Myc-induced lymphomas markedly impairs cell growth by inhibiting protein synthesis rates." (PMID 36651285, 2023). "In addition, studies found that malignant pleural mesothelioma tumors contained high levels of hyperphosphorylated eIF6, and dephosphorylated eIF6 significantly reduced the growth and metastasis of tumor cells." (PMID 34922580, 2021). "To study whether eIF6 protein was expressed in malignant pleural mesothelioma (MPM), we performed an immunohistochemistry staining on 24 human MPM samples from an Italian cohort, using an anti-eIF6 polyclonal antibody." (PMID 26462016, 2015).
non-alcoholic fatty liver disease (4 papers, 2021 to 2025). "Deletion of one allele of eIF6 dramatically reduces lymphomagenesis and the transition from NAFLD (non-alcoholic fatty liver disease) to hepatocellular carcinoma." (PMID 39001453, 2024).
non-small cell lung carcinoma (4 papers, 2019 to 2022). A group of at least three distinct histological types of lung cancer, including non-small cell squamous cell carcinoma, adenocarcinoma, and large cell carcinoma. "In a recent study, the knockdown of eIF6 in adenocarcinoma and squamous cell carcinoma led to pre-rRNA processing and ribosomal 60S maturation defects, and in non-small-cell lung cancer, there was upregulation of eIF6." (PMID 34285764, 2021). "eIF6 was found to be overexpressed in various cancer types, like colorectal cancer, ovarian serous carcinoma, acute promyelocytic leukemia, non-small cell lung cancer and in head and neck cancer." (PMID 31586263, 2019). "eIF6 was found to be overexpressed in various cancer types, like metastatic colorectal cancer (CRC) or non-small cell lung cancer." (PMID 31586263, 2019).
Obesity (4 papers, 2015 to 2025). Accumulation of substantial excess body fat. "Taken together, these findings demonstrate that 50% eIF6 depletion protects mice from diet-induced obesity and diminishes the progression to aggressive liver cancer." (PMID 34385447, 2021). "The previous observations raised the possibility that interfering with eIF6 activity would interrupt the translational reinforcement of de novo lipogenesis, with a strong impact on all aspects of the evolution from obesity to HCC." (PMID 34385447, 2021). "We provide a mechanistic link between obesity and cancer through eIF6 activity." (PMID 26383020, 2015). "Since obesity, type 2 diabetes, and cancer require a Fasn-driven lipogenic state, we propose that eIF6 could be a therapeutic target for these diseases." (PMID 26383020, 2015). "Unlike the obesity phenotype observed upon whole-body knockdown of eif-6 in C. elegans fed a regular diet, Eif6 heterozygous mice had reduced body weight gain compared to their wild-type littermates." (PMID 34492009, 2021).
ovarian carcinoma (4 papers, 2008 to 2021). A malignant neoplasm originating from the surface ovarian epithelium. "Overall, the outcome of these experiments confirmed and extended the previous results observed in ovarian cancer cell lines, i.e. that eIF6 is implicated in the control of cell motility/invasiveness, also in different cellular contexts." (PMID 25886394, 2015). "Here, we performed a quantitative proteomic analysis of membrane-associated proteins in A2780 ovarian cancer cells over-expressing eIF6." (PMID 25886394, 2015). "Although relevant studies have confirmed that the GABP complex regulates the transcription of eIF6 and that the Notch-l signaling pathway stimulates the activity of eIF6 promoter in lymphoblastoid and ovarian cancer cell lines." (PMID 34016142, 2021). "In a previous work we observed that eIF6 over-expression in A2780 ovarian cancer cells stimulated their motility and invasiveness." (PMID 25886394, 2015). "Inhibition of Notch-1 signaling in ovarian cancer cells by γ-secretase inhibitors slowed down cell-cycle progression and decreased the level of eIF6 protein." (PMID 25886394, 2015). "Inhibition of Notch-1 signalling by γ-secretase inhibitors slowed down cell-cycle progression and reduced the amount of eIF6 in lymphoblastoid and ovarian cancer cell lines." (PMID 22348144, 2012). "Furthermore, the Notch1/RBPJ signaling pathway stimulates eIF6 promoter activity, enhancing the expression of eIF6 and the invasiveness of ovarian cancer cells." (PMID 34016142, 2021). "Thus, we investigated whether eIF6 over-expression could induce the activation of cdc42-Pak signalling in A2780 ovarian cancer cells." (PMID 25886394, 2015). "This confirms previous reported studies, where eIF6 knockdown in CRC cells significantly reduced proliferation and colonogenicity, while eIF6 overexpression enhanced the migratory phenotype by augmenting CDC42 translation in ovarian cancer." (PMID 34016142, 2021). "Regarding the for downstream regulation of eIF6, existing studies have demonstrated that eIF6 could indirectly regulate Wnt/-catenin signaling in CRC cells and affect CDC42 signaling in ovarian cancer cells, which promotes migration and invasion." (PMID 34016142, 2021).
ovarian serous carcinoma (4 papers, 2017 to 2022). "Another study showed that high eIF6 expression is significantly associated with clinicopathological features, such as lymph node metastases in ovarian serous carcinoma." (PMID 35794622, 2022).